THBD (thrombomodulin)
Diseases named in the same sentence as THBD in open-access papers (continued):
Sharing a sentence is not in itself a finding about the gene and the disease.
Gastric Metaplasia (1 paper, 2019). Intestinal metaplasia of the gastric mucosa is an intermediate precancerous gastric lesion in the gastric cancer cascade from chronic gastritis and atrophy to dysplasia and adenocarcinoma. "For example, hypermethylation of APC, THBD, and HAND1 was associated with gastric metaplasia." (PMID 31537016, 2019).
glomerulosclerosis (1 paper, 2026). A hardening of the kidney glomerulus caused by scarring of the blood vessels. "We assessed microthrombi, tubular necrosis, glomerulosclerosis, fibrosis, and expression of angiopoietin-2 and thrombomodulin." (PMID 41620635, 2026).
heart failure (1 paper, 2008). Inability of the heart to pump blood at an adequate rate to meet tissue metabolic requirements. "Erythropoietin and thrombomodulin have also been shown to play a role in endothelial function and heart failure." (PMID 18800166, 2008).
Heat Stroke (1 paper, 2025). A condition caused by the failure of body to dissipate heat in an excessively hot environment or during PHYSICAL EXERTION in a hot environment. "The administration of thrombomodulin has been shown to alleviate heat stroke-induced multi-barrier dysfunction by mitigating intestinal hyperpermeability and blood-brain barrier disruption." (PMID 40703654, 2025).
hematoma (1 paper, 2022). A hematoma is a collection of blood from a vascular structure into an extravascular space. "It is, thus, noteworthy that levels of thrombomodulin are significantly higher in hematoma fluid of CSDH compared to peripheral blood, a finding that has been associated with hematoma outer membrane vessel damage, inhibition of hematoma thrombus formation and hematoma expansion." (PMID 36010216, 2022).
homocystinuria (1 paper, 2020). An autosomal recessive inherited metabolic disorder caused by mutations in the CBS, MTHFR, MTR, and MTRR genes. "Recently, it has been identified that mutation in non-complement genes such as diacylglycerol kinase epsilon (DGKE), thrombomodulin (THBD), inverted formin 2 (INF2) and methylmalonic aciduria and homocystinuria cobalamin C (cbLC) type (MMACHC) can also trigger aHUS." (PMID 32838746, 2020).
Hypercalcemia (1 paper, 2022). An abnormally increased calcium concentration in the blood. "In turn, the second analyzed endothelial damage biomarker, thrombomodulin, was higher in patients with hypercalcemia." (PMID 36494464, 2022). "The coexistence of extrapulmonary disease was associated with elevated circulating vascular cell adhesion molecule 1, while cases with hypercalcemia had higher thrombomodulin concentration." (PMID 36494464, 2022). "Furthermore, those with documented prolonged hypercalcemia were characterized by increased thrombomodulin in peripheral blood (6305 [95% CI 5175–7436] ng/ml, n = 11, vs. 4997 [95% CI 4668–5327] ng/ml, n = 42; p = 0.002)." (PMID 36494464, 2022). "Thus, higher thrombomodulin in hypercalcemia might also be related to the macrophage stimulation in sarcoid granulomas." (PMID 36494464, 2022).
hypercortisolism (1 paper, 2022). "The endogenous thrombin potential (ETP) measured with and without the addition of thrombomodulin provides a global representation of coagulation and previous data confirmed hypercoagulable profile in patients with active hypercortisolism." (PMID 34115342, 2022).
Hypoglycemia (1 paper, 2024). A decreased concentration of glucose in the blood. "However, we did observe a reduction in thrombomodulin during same-day recovery from hypoglycemia only when induced under resting conditions." (PMID 38642404, 2024). "Thrombomodulin showed no significant changes from baseline during hypoglycemia on either of the test days; however, a decrease from baseline was observed after 30 minutes of recovery on Hypo-rest only." (PMID 38642404, 2024).
hypoprothrombinemia (1 paper, 2021). "Conversely, the use of ROTEM in evaluating the coagulation status of cirrhotic patients may be less accurate because of hypoprothrombinemia and lack of sensitivity to thrombomodulin." (PMID 34362183, 2021).
hypovitaminosis (1 paper, 2019). "Treatment of hypovitaminosis has been shown to decrease SOFA scores, PCT, C-reactive protein, and thrombomodulin levels, which can translate to decreases in organ failure, inflammation, and endothelial injury." (PMID 30970560, 2019).
intrauterine growth restriction (1 paper, 2016). "Furthermore, increased levels of THBD in the maternal circulation negatively correlate to infant birth weight, and the highest plasma THBD level was detected in PE pregnancy with intrauterine growth restriction, which is often associated with early-onset PE." (PMID 27780539, 2016).
left ventricular hypertrophy (1 paper, 2018). Enlargement of the LEFT VENTRICLE of the heart. "In the studied group of children with CKD, thrombomodulin correlated well with BNP, a marker of myocardial stress, and LVMI, a marker of left ventricular hypertrophy." (PMID 29682152, 2018).
leprosy (1 paper, 2016). Leprosy is a chronic infectious disease affecting primarily the skin and peripheral nervous system. "The present study evaluated the expression ofendothelial factors in skin lesions and serum samples of leprosy patients.Immunohistochemical analysis of skin samples and serum measurements of VCAM-1, VEGF,tissue factor and thrombomodulin were performed in 77 leprosy patients and 12controls." (PMID 27706378, 2016). "Patients with type 1 reaction presented increased thrombomodulin serumlevels, compared with non-reactional leprosy (p = 0.02)." (PMID 27706378, 2016).
lung squamous cell carcinoma (1 paper, 2017). "Desmocollin-3 was the most specific marker for poorly differentiated squamous cell lung carcinoma (100%), followed by CK5/6 (98.3%), glypican-3 (94.8%), Sox2 (94.8%), S100A2 (81%), S100A7 (75.9%), thrombomodulin (72.4%), p63 (48.3%), and HMCK (36.8%)." (PMID 28510121, 2017). "When analyzing only poorly differentiated tumors, HMCK was the most sensitive marker for squamous cell lung carcinoma (100%), followed by p63 (97.8%), CK5/6 (87.0%), Sox2 (71.7%), thrombomodulin (58.7%), desmocollin-3 (52.2%), S100A2 (50%), glypican-3 (45.7%), and S100A7 (45.7%)." (PMID 28510121, 2017).
Menorrhagia (1 paper, 2021). Prolonged and excessive menses at regular intervals in excess of 80 mL or lasting longer than 7 days. "TGF-β3 also plays a crucial role in UF-associated HMB, leading to the reduced expressions of thrombomodulin, PAI-1, and ATIII in the endometrium, likely contributing to menorrhagia." (PMID 34113609, 2021).
mesenchymal neoplasms (1 paper, 2023). "After exclusion of reactive processes, carcinomas, and mesenchymal neoplasms, additional EMA, desmin, IMP‐3, and thrombomodulin positivity can be observed in the majority of cases, alongside with BAP1 loss." (PMID 36808895, 2023).
nephrotic syndrome (1 paper, 2021). A collection of symptoms that include severe edema, proteinuria, and hypoalbuminemia; it is indicative of renal dysfunction. "Nephrotic syndrome can cause a plasma soluble thrombomodulin, and von Willebrand factor levels that can contribute to the development of TMA." (PMID 34646728, 2021).
non-small cell lung carcinoma (1 paper, 2025). A group of at least three distinct histological types of lung cancer, including non-small cell squamous cell carcinoma, adenocarcinoma, and large cell carcinoma. "A different study has shown that a decrease in thrombomodulin expression is associated with increased tumor cell invasion and a poorer prognosis in non-small cell lung cancer." (PMID 40332167, 2025).
renal dysfunction (1 paper, 2022). "Human soluble recombinant thrombomodulin (TM alfa), a treatment for septic Disseminated intravascular coagulation (DIC), is recommended for patients with severe renal dysfunction in reduced doses." (PMID 36503588, 2022).
silicosis (1 paper, 2022). Silicosis is a respiratory disease caused by breathing in (inhaling) silica dust. "For the first time, we found that cellular adhesion molecules (CAM), such as Gm2a, CHI3L1, LCN2, THBD, NADPH oxidase (NOXs) and vacuolar-ATPase are involved in pathogenesis of silicosis." (PMID 34991559, 2022).
squamous cell carcinoma (1 paper, 2021). A carcinoma arising from squamous epithelial cells. "Thrombomodulin was particularly expressed in squamous carcinomas as well as cytokeratin, while 53% of adenocarcinomas immunoreacted with mesothelin." (PMID 34070888, 2021).
systemic sclerosis (1 paper, 2025). A chronic disorder, possibly autoimmune, marked by excessive production of collagen which results in hardening and thickening of body tissues. "In individuals with systemic sclerosis who also present with Raynaud’s phenomenon, plasma levels of thrombomodulin have been reported to be markedly higher." (PMID 40559115, 2025).
uterine corpus endometrial carcinoma (1 paper, 2025). A endometrial carcinoma (disease) that involves the body of uterus. "Thrombomodulin (THBD), hsa-miR-18a-5p, and hsa-miR-18b-5p have been frequently mentioned in numerous cancer-related research studies; however, their specific functions in uterine corpus endometrial carcinoma (UCEC) are not well understood." (PMID 40332167, 2025).
uveitis (1 paper, 2013). An inflammatory process affecting a part of or the entire uvea. "It has been documented that GC31, a 31-animo acid peptide from human thrombomodulin, has potent anti-inflammatory properties in endotoxin-induced uveitis and lipopolysaccharide (LPS)-induced RAW264.7 cells, while the role of GC31 in the endothelial cells has not yet been fully understood." (PMID 23401649, 2013). "We previously demonstrated that the peptide GC31, which is derived from C-type lectin-like domain (CTLD) of human thrombomodulin (TM), has a potent anti-inflammatory effect on endotoxin-induced uveitis (EIU) by reducing leukocyte infiltration and proinflammatory mediator expression." (PMID 23401649, 2013).
tumor (122 papers, 2002 to 2026). "Conversely, the molecules that were found to be more highly enriched in hTERT-immortalized MSC EVs (i.e., THY-1, Thrombomodulin, Neprilysin) have been associated with reparative, tumor suppressive, and anti-inflammatory properties." (PMID 38786083, 2024). "Due to its tumour suppressive properties, loss of thrombomodulin observed in this present study, could potentially cause increased tissue differentiation, metastasis and recurrence." (PMID 33238953, 2020). "Only advanced-stage EOCs appeared to be characterized by a scenario that involves genes such as FPR1, KLF2 and THBD, to date associated with thrombosis and cardiovascular disease, thus suggesting that this pathway contributes to the growth and/or the spread of this type of tumor." (PMID 23889749, 2013). "The presence of atypical thrombomodulin expression in tumor tissues has been documented, raising important questions about its function in tumorigenesis, progression, and metastasis." (PMID 40332167, 2025). "Those with elevated THBD levels commonly presented a high KS (χ2, p < 0.05), suggesting a potential role in the tumour coagulome." (PMID 39001418, 2024). "Some of them, including CCL4, IL10, and THBD, have well-studied mechanisms that contribute to tumor growth promotion." (PMID 38832259, 2024). "The tumor expression of thrombomodulin (TM) is correlated with favorable prognosis in several types of cancer." (PMID 37239055, 2023). "This tumor angiogenesis core gene signature also included CLEC14A and CD93, which together with endosialin and thrombomodulin constitute a C-type lectin family that are frequently up-regulated in tumor vessels." (PMID 31690961, 2020). "Tumor samples with high levels of THBD mRNA (median split) were significantly enriched of CD56dim NK cells in both Nanostring-NB and SEQC-NB cohorts, as well as high levels of NCR1 mRNA were associated with an abundance of intratumoral DCs." (PMID 33239635, 2020). "RNAscope analysis, performed to visualize the cell types expressing THBD, showed that THBD transcript was highly expressed in tumor-infiltrating immune cells resembling myeloid morphology in NB tissues." (PMID 33239635, 2020). "Thrombomodulin is a tumor suppressive protein that when expressed in several types of cancer cells decreased tumor invasiveness and improved patient survival." (PMID 30626007, 2019). "Thrombomodulin, CD93 and CLEC14A can be expressed by endothelial cells, whereas CD248 is expressed by vasculature associated pericytes, activated fibroblasts and tumour cells among other cell types." (PMID 31287944, 2019). "The overall findings seem to indicate that thrombomodulin expression correlates with a good prognosis and expression is abolished in more aggressive and highly metastatic tumour types." (PMID 31287944, 2019). "Another cell surface protein that is found to be cleaved by RHBDL2 in (non-tumor) epithelial cells is thrombomodulin." (PMID 31783481, 2019). "Further immunohistochemical study was performed, and the tumor cells were positive for low and high molecular weight cytokeratin and thrombomodulin and focally positive for CEA." (PMID 25849448, 2015). "BLCA-4 activity is mediated by IL-1, IL-8, and thrombomodulin, which can act by maintaining blood flow for tumor cell survival, enhancing tumor cell proliferation and invasion, and increasing tumor angiogenesis." (PMID 22811704, 2012). "Approaches such as miRNA-based therapies (e.g., miR-18a-5p inhibitors), epigenetic modifiers, or THBD gene replacement techniques may represent promising avenues to counteract tumor progression and improve clinical outcomes in UCEC patients." (PMID 40332167, 2025). "Beyond hypercoagulability and systemic inflammation, direct vascular compression or infiltration by the tumor, as well as disruptions in natural anticoagulant pathways - particularly involving protein C and thrombomodulin - play key roles in the pathophysiology of this complication." (PMID 40978872, 2025).
tumor (continued). "The staining of tumor cells with the HPA002982 (Anti-THBD antibody) revealed a medium intensity." (PMID 40332167, 2025). "Our integrated bioinformatics and experimental analyses suggest that miR-18a-5p may function as a key oncogenic regulator in UCEC pathogenesis by promoting tumor cell proliferation, migration, and invasion, in part through the suppression of THBD expression." (PMID 40332167, 2025). "Notably, there was a positive association between the levels of ARGs and CNV alteration; for example, the expression levels of PRG2, SERPINA5, and THBD were low in tumor tissues, while VEGFA, PF4, and PTK2 were expressed at high levels." (PMID 37938164, 2023). "Interestingly, both THBD and H2AFJ were significantly positively correlated with the main tumor-associated immunosuppressive cells, including Treg cells, MDSCs, NK cells and macrophages." (PMID 32857727, 2020). "Furthermore, the soluble ECD of thrombomodulin has also been reported to reduce tumour growth in inflamed models of gastrointestinal tumours." (PMID 31287944, 2019). "In immunohistochemistry, a panel of different antibodies, such as carcinoembryonic antigen (CEA), gastrin-releasing peptide (GRP), cytokeratin (CK) 5/6, thyroid transcription factor 1 (TTF-1), p63, and thrombomodulin (CD141), is applied for biomarker detection on tumor cells." (PMID 28325282, 2017). "The neoplasms were positive for high molecular weight keratin (34BetaE12) and thrombomodulin." (PMID 27256178, 2016). "PVTT formation may be facilitated by thrombomodulin, which inhibits plasma antithrombase factor and P-selection, through circulating tumor cell adhesion at an early stage." (PMID 27027235, 2016). "In this study, we found that CUR enhances the promoter activity of E-cad and thrombomodulin suggesting that an increased E-cad expression might stabilize the CRC cell-cell contact that prevents tumor cell migration." (PMID 23970932, 2013). "In these tumours, the expression level of THBD is inversely correlated with malignancy of cancer." (PMID 15900300, 2005). "This immunosuppressive role of thrombomodulin could also have relevance in tumour immunology as thrombomodulin expressed in the tumour microenvironment has the potential to expand anti‐inflammatory and protumour Tregs, a cell type that contributes to tumour immune evasion mechanisms." (PMID 31287944, 2019). "The thrombomodulin–fibronectin interaction occurs on tumour blood vessels in murine melanoma suggesting that this interplay may serve as a putative target for antiangiogenic therapy, although an in‐depth understanding of this interaction in healthy tissues would first need to be considered." (PMID 31287944, 2019). "Among these genes, EFNA4 and TEDC2 were significantly upregulated, whereas CDC42EP2, STX11, THBD, TMEM88, and GPM6A were notably downregulated in tumor tissues compared with adjacent normal tissues." (PMID 42196266, 2026). "The release of CCL4 aids in tumor invasion, IL10 plays a role in immunosuppression, and THBD contributes to enhanced resistance to TMZ." (PMID 38832259, 2024). "We also detected other epigenetically regulated genes in this signature, including CD70, IRAK, IL20RA, THBD, TACSTD2, and MST1R, with implications related to the tumor immune microenvironment." (PMID 34150764, 2021). "CD93 is a member of group XIV in the C-type lectin superfamily, which also includes thrombomodulin, CLEC14A, and endosialin, all of which are highly expressed in tumor vessels." (PMID 29763414, 2018). "Indeed, IL-33 expression correlated strongly with CD8A and granzyme B as well as genes like BATF3, IRF8, THBD, CLEC9, and XCR1 that are required for tumor antigen cross-presentation functionality of CD103+ dendritic cells (DCs)." (PMID 36256464, 2022). "CDX2 and villin immunostains were also positive; thrombomodulin was positive in tumor vessels but not within the tumor cells themselves." (PMID 27006847, 2016).
tumor (continued). "Immunohistochemically, the tumor cells express cytokeratin, calretinin, D2-40, thrombomodulin, and nuclear WT1 but are negative for Ber-EP4, CEA, CD15, and CD34." (PMID 27293940, 2016). "Moreover, ligands implicated in the interaction between THBD+ macrophages and malignant tumour cells were identified, including SPP1‐(ITGAV+ITGB1) and APP‐CD74, suggesting the potential of THBD+ macrophages to influence malignant tumour cells through diverse ligands." (PMID 38809929, 2024). "Interestingly, THY-1, Thrombomodulin, and Neprilysin, which were more highly enriched in hTERT-immortalized MSC EVs, may have potential roles in biological processes related to inflammation, tumor suppression, cellular differentiation and migration, regeneration, and apoptosis." (PMID 38786083, 2024).